CDC25B (cell division cycle 25B)
Diseases named in the same sentence as CDC25B in open-access papers (continued):
Sharing a sentence is not in itself a finding about the gene and the disease.
tumor (continued). "In GC samples from a Chinese population, a correlation between MYC and CDC25B immunoreactivity was described; however, the effect of tumor stage in the immunoreactivity of these proteins was not accessed." (PMID 27863420, 2016). "Although higher levels of anti-CDC25B antibodies were found in the sera of patients with ESCC than in the sera of healthy controls, the relationship between tumor burden, tumor staging and antibody levels remains unknown." (PMID 20813067, 2010). "Based on our encouraging data with CDC25B specific siRNA, we propose that siRNA may offer a new approach to targeting CDC25B expression and activity in HCC and other malignancies, leading to inhibitions of tumor cell growth and invasion." (PMID 18269767, 2008). "We previously identified CDC25B mRNA to be significantly up-regulated in human HCC tumor compared to non-tumor liver tissues." (PMID 18269767, 2008). "We found that FOXM1a overexpression significantly decreased the expression of CDC25B, PLK1, and CCNB1 in both CAL 27 and SCC-9 cells, indicating that FOXM1a may inhibit cell proliferation and tumor formation through downregulating the expression of these key genes." (PMID 37759731, 2023). "Immunization with either CDC25B or COX-2 epitopes could inhibit and even prevent tumor growth." (PMID 34526999, 2021). "Thus, although CDC25B overexpression is not sufficient to induce tumor growth, it impacts positively toward tumorigenesis." (PMID 33745968, 2021). "P‐MAPK14 and CDC25B were not correlated with gender, age, or tumor stage." (PMID 31856414, 2020). "Our results showed that the tumor suppressors CDKN1A (also known as Cip1 and p21) and GADD45 were downregulated while various positive cell-cycle regulators and components for DNA replication, including cyclin-B, cyclin-D, CDK1, CDC25B, and MCMs, were upregulated by TSPY-overexpression." (PMID 30867900, 2019). "However, it is important to highlight that only two samples presented the ratio of CDC25B protein expression between tumor and corresponding non-neoplastic specimens below 1 in the studied cohort." (PMID 27863420, 2016). "The mechanisms by which the CDC25B level becomes deregulated in tumours remains unclear but it does not appear that the overexpression results from gene amplification or rearrangement." (PMID 20128929, 2010). "Cdc25B was not expressed in normal follicular cells or stromal cells, including lymphocytes and epithelial cells of the blood vessels (not shown), whereas it was predominantly expressed in the cytoplasms of tumour cells." (PMID 12085185, 2002). "In addition, high CDC25B expression contributed to the poor prognosis of HCC patients by altering the abundance of lymphocyte infiltration, creating an overactive TME, and upregulating some immune checkpoints, which exacerbated the immune evasion mechanism of the tumor." (PMID 39371450, 2024). "However, the specific mechanism by which increased Cdc25B impacts tumor progression is not clear." (PMID 33745968, 2021). "Moreover, the mRNA of several cell cycle regulatory genes, such as Cdc25b, Cyclin B1, Cyclin A2, Plk1, Cks1, Aurora B, and Topo 2 alpha were decreased in prostates of TRAMP/SPDEF OE mice, a finding consistent with decreased cellular proliferation and decreased tumor sizes." (PMID 25254494, 2014). "YWHAE expression seems to increase and CDC25B expression seems to reduce between stages I and III; however, we did not detect a significant change among tumor stages after Bonferroni adjustment (p>0.008)." (PMID 27863420, 2016). "In the tumor initiation, the opposite role of YWHAE and CDC25B in gastric carcinogenesis seems to be independent of MYC expression." (PMID 27863420, 2016). "RT-PCR analysis of the transcriptional expression of cell cycle genes showed a significantly increased expression of ccnA1, ccnB2, ccnD3, ccnE1, cdc25b, and E2F1 and a significantly decreased expression of ccnD2 in the Fhit-transfected versus non-transfected tumor cells." (PMID 32545680, 2020).
infection (5 papers, 2010 to 2021). The state of being infected such as from the introduction of a foreign agent such as serum, vaccine, antigenic substance or organism. "The multiplicity of infection (MOI) value equivalent to 60 was chosen for subsequent experiments as this MOI efficiently expressed CDC25B or GFP." (PMID 33745968, 2021). "The expression of 38 genes associated with cell growth and death were significantly up-regulated by ORFV infection at 8 h post-infection, except for CDC25B and FOS." (PMID 28938587, 2017). "While NR-1ΔmiR-UL148D infection resulted in sustained inhibition of CDC25B, HCMV IE1 expression was suppressed when the constitutively activated CDK1 mutant was overexpressed in host cells." (PMID 27824944, 2016). "Concordant with this observation, CDC25B levels decreased in Kasumi-3 cells during the early days of infection." (PMID 27824944, 2016). "In the Kasumi-3 cells infected with NR-1ΔmiR-UL148D, incubation with the miR-UL148D agomir strongly suppressed IER5 expression but restored CDC25B levels at late stages of infection." (PMID 27824944, 2016). "Our result showed that infection of HPV correlated with high expression of CDC25B and nuclear phospho-CDC25C (Ser216)." (PMID 20500813, 2010). "Infection with NR-1ΔmiR-UL148D, a derivative of the HCMV clinical strain NR-1 with a miR-UL148D knockout mutation, resulted in sustained induction of IER5 expression but decreased CDC25B expression in host cells." (PMID 27824944, 2016). "During infection of CD34+ HPCs with a miR-UL148D mutant, levels of IER5 protein were significantly increased, while CDC25B showed a concordant decrease in expression." (PMID 33668486, 2021). "On the contrary, during the late stages of NR-1ΔmiR-UL148D infection, IER5 expression was maintained at a high level in infected cells, while CDC25B expression was virtually undetectable." (PMID 27824944, 2016). "During the early stages of NR-1 and NR-1ΔmiR-UL148D infection, IER5 expression in host cells rapidly increased, which was correlated with a decrease in CDC25B expression." (PMID 27824944, 2016). "As shown, infection with LV-IER5 resulted in continuous high-level expression of IER5 in the NR-1-infected Kasumi-3 cells, even at late stages of infection, whereas CDC25B expression was significantly decreased along the 10-day time course." (PMID 27824944, 2016). "Using the myeloid cell line Kasumi-3, the authors show that infection with the miR-UL148D mutant virus does not inhibit IE1 gene expression due to the enhanced phosphorylation of CDK-1 that occurs upon reduced CDC25B expression." (PMID 33668486, 2021). "In contrast, possibly due to the lack of miR-UL148D, both the Kasumi-3 cells and the CD34+ HPCs that were infected with NR-1ΔmiR-UL148D failed to suppress IER5 expression at later stages of infection, leading to sustained inhibition of CDC25B." (PMID 27824944, 2016). "However, compared to 4 days post infection, IER5 levels in Kasumi-3 cells and CD34+ HPCs infected with NR-1 significantly decreased at later stages of infection (7–10 dpi), while levels of CDC25B expression were restored." (PMID 27824944, 2016). "In the Kasumi-3 cells infected with NR-1, the transcripts level of IE1, UL54 and UL99 remained low even at late stages of infection, regardless of the overexpression of CDC25B, although overexpression of CDC25B reduced the increase in IE1 transcription at early stages of infection." (PMID 27824944, 2016).
immune diseases (1 paper, 2023). "The component-target-disease network diagram revealed that the essential oil compositions in leaves of C. grandis ‘Tomentosa’ could treat tumors, immune diseases, neurodegenerative diseases and respiratory diseases, which were highly related to CHRM1, PTGS2, CASP3, MAP2K1 and CDC25B." (PMID 35702766, 2023).
prostate (1 paper, 2013). "Despite that, the function of Cdc25B to AR is independent of its cell cycle function; Cdc25B is proposed to play a role in human prostate carcinogenesis." (PMID 23637932, 2013).
CDC25B also shares sentences with these, for which no sentence is quoted: dilated cardiomyopathy (2 papers); endometrial carcinoma (2); glioma (2); pheochromocytoma (2); renal cell carcinoma (2); bacterial infections (1); benign adenoma (1); cervical tumor (1); childhood asthma (1); cocaine abuse (1); endocrinopathies (1); kidney chromophobe (1); latent infection (1); lung adenocarcinoma (1); nasopharyngeal carcinoma (1); neurodegenerative disease (1); neurological diseases (1); ovarian serous cystadenocarcinoma (1); papillary carcinoma (1); pituitary tumour (1); preeclampsia (1); prion disease (1); respiratory diseases (1); schizophrenia (1); skin squamous cell carcinoma (1); T-cell leukemia (1); testicular cancer (1); testicular germ cell tumor (1); undifferentiated carcinoma (1); uterine corpus endometrial carcinoma (1).